TBC1D21 (TBC1 domain family member 21)
Description:
Acts as a GTPase-activating protein for Rab family protein(s). Essential for the establishment of male fertility, and is required for both the production of normal sperm number and sperm function (By similarity). Plays an important role in the formation of intact mitochondria, outer dense fibers and axoneme within the sperm tail (By similarity). Essential for sperm mitochondrial sheath formation and for the interactions of ARMC12 with VDAC2 and VDAC3 (By similarity). May be involved in acrosome formation and cytoskeletal reorganization during spermiogenesis, possibly by regulating RAB3A activity.
Synonyms: MGCRABGAP; MGC34741
Tractability: No criterion of Open Targets' tractability assessment is met for any kind of drug.
Gene: Protein-coding gene on chromosome 15 (73,873,564 to 73,889,214, forward strand). Ensembl gene ENSG00000167139.
Subcellular location: Cytoplasmic vesicle, secretory vesicle, acrosome; Cytoplasm, cytoskeleton
Subcellular location (Human Protein Atlas): Calyx; Mid piece
Gene Ontology:
Molecular function: GTPase activator activity; protein binding; small GTPase binding; actin binding
Biological process: regulation of cilium assembly; flagellated sperm motility; plasma membrane to endosome transport; sperm axoneme assembly; sperm mitochondrial sheath assembly; spermatogenesis
Cellular component: extracellular exosome; cytoplasmic vesicle; sperm midpiece; acrosomal vesicle; cytoskeleton
Genetic constraint (gnomAD): Loss-of-function variants: 38 observed, 47.35 expected, observed/expected ratio (o/e) 0.8, 90% interval 0.62 to 1.05. The upper end of that interval is the gene's LOEUF score, 1.05, which puts it in group 4 of 6, group 1 being the genes least tolerant of losing a copy. Missense variants: 415 observed, 437.96 expected, observed/expected ratio (o/e) 0.95, 90% interval 0.87 to 1.03. Synonymous variants: 151 observed, 164 expected, observed/expected ratio (o/e) 0.92, 90% interval 0.81 to 1.05.
Homologues: Orthologues: chimpanzee TBC1D21 (99% identical), macaque TBC1D21 (97% identical), pig TBC1D21 (92% identical), dog TBC1D21 (90% identical), mouse Tbc1d21 (87% identical), guinea pig TBC1D21 (87% identical), rat Tbc1d21 (87% identical). Paralogues in human: TBC1D17 (21% identical), TBC1D16 (21% identical), TBC1D15 (20% identical), TBC1D8 (20% identical), TBC1D9B (19% identical), TBC1D9 (18% identical), TBC1D8B (18% identical), TBC1D2B (18% identical), TBC1D1 (18% identical), TBC1D10C (17% identical), TBC1D10A (17% identical), TBC1D25 (17% identical), and 33 more.
Diseases named in the same sentence as TBC1D21 in open-access papers:
TBC1D21 is named in the same sentence as 7 diseases in open-access papers, as found by Europe PMC text mining. Sharing a sentence is not in itself a finding about the gene and the disease. The quoted sentences say what the papers report.
male infertility (4 papers, 2018 to 2023). The inability of the male to effect fertilization of an ovum after a specified period of unprotected intercourse. "Because TBC1 domain family protein TBC1D21 is the only TBC1 domain family protein showing testis-enriched expression in mice and disruption of Tbc1d21 causes male infertility with morphological abnormalities of the sperm mitochondria, we focused on TBC1D21." (PMID 33536340, 2021). "TBC1D21 is expressed late in spermatids and localizes to the acrosome and midpiece, and the disruption of TBC1D21 causes male infertility with morphological abnormalities of the sperm mitochondria and flagellum in mice." (PMID 33536340, 2021). "Loss of Tbc1d21 in mice caused male infertility, characterized by decreased sperm motility, and sperm tail defects." (PMID 32976492, 2020). "Here, we show that loss of Tbc1d21 in mice resulted in male infertility, characterized by defects in sperm tail structure and diminished sperm motility." (PMID 32976492, 2020). "In our previous studies, we identified TBC1D21 as a sterility-related GAP associated with male infertility as well as a testis-specific expressed gene." (PMID 32976492, 2020). "Targeted disruption of Tbc1d21 induces male infertility in mice." (PMID 32976492, 2020). "We performed Cr‐CEST by using 7T MRI on wild‐type C57B6/J mice and several types of male infertility models such as Sertoli‐cell only (SCO) (Kitw/Kitwv), maturation arrest (MA) (Zfp541 knockout mouse and Kctd19 knockout mouse), and teratozoospermia (Tbc1d21 knockout mouse)." (PMID 36845001, 2023).
infertile (2 papers, 2018 to 2020). "A clinical study, including hypospermatogenesis, maturation arrest, and Sertoli-cell-only cases, reports that TBC1D21 transcript levels in testicular tissue are lower in infertile men than in fertile men." (PMID 30360518, 2018). "We previously identified TBC1D21 as a sterility-related RabGAP gene derived from infertile men." (PMID 32976492, 2020). "However, whether dysregulation or genetic alterations of TBC1D21/TBC1D21 are also involved in infertility in men remains unclear." (PMID 32976492, 2020).
sterility (2 papers, 2018 to 2020). "TBC1D21 genes (also known as male germ cell RAB GTPase-activating protein MGCRABGAP) are related to sterility, as determined through cDNA microarray testing of human testicular tissues exhibiting spermatogenic defects." (PMID 30360518, 2018). "We previously identified TBC1D21 as a sterility-related RabGAP gene from infertile men." (PMID 32976492, 2020).
teratozoospermia (2 papers, 2020 to 2023). "From a clinical perspective, TBC1D21 transcripts are reduced in sperm from patients exhibiting teratozoospermia." (PMID 32976492, 2020). "In the current study, we investigated TBC1D21, expressed in human post-meiosis male germ cells, and observed a decrease in the TBC1D21 expression in sperm samples from teratozoospermia patients." (PMID 32976492, 2020). "From a clinical perspective, TBC1D21 transcripts are decreased in sperm from teratozoospermia patients." (PMID 32976492, 2020). "From a clinical perspective, the transcript levels of TBC1D21 in sperm from teratozoospermia cases were significantly reduced when compared with those in normozoospermia." (PMID 32976492, 2020).
TBC1D21 also shares sentences with these, for which no sentence is quoted: embryonal carcinoma (1 paper); glaucoma (1); skin cutaneous melanoma (1).